CD68 (CD68 molecule)
Diseases named in the same sentence as CD68 in open-access papers (continued):
Sharing a sentence is not in itself a finding about the gene and the disease.
endothelial dysfunction (7 papers, 2012 to 2025). In vascular diseases, endothelial dysfunction is a systemic pathological state of the endothelium (the inner lining of blood vessels) and can be broadly defined as an imbalance between vasodilating and vasoconstricting substances produced by (or acting on) the endothelium. "As expected, mRNA expressions of the monocyte marker CD68, the endothelial dysfunction marker CD146, the monocyte chemoattractant protein-1 (MCP-1), and the interleukin-6 (IL-6), were significantly upregulated since 6 h of renal IR." (PMID 39707203, 2024). "We previously reported increased infiltration of CD8 T cells and CD68+ myeloid cells (monocytes/macrophages) at sites of endothelial dysfunction in aortas of RMs with SHIV and SIV infections." (PMID 32976527, 2020). "Oxysterols promote endothelial dysfunction by different routes: they accumulate in foam cells (CD68+ macrophages) and generate large subendothelial deposits constituting “acute atherosis” of the spiral arteries, which is histologically similar to chronic atherosclerosis." (PMID 35631313, 2022). "Interestingly, mice subjected to the AFD regimen displayed downregulated expression levels of the endothelial dysfunction marker endothelin-1, the inflammatory markers MCP-1 and CD68 and the fibrosis markers desmin when compared to HFD fed mice." (PMID 23049881, 2012).
esophageal cancer (7 papers, 2014 to 2025). A primary or metastatic malignant neoplasm involving the esophagus. "CD68+ macrophage infiltration in esophageal cancer is associated with better prognosis." (PMID 31781681, 2019). "CD68 mRNA expression was significantly higher in esophageal carcinoma (ESCA) and stomach adenocarcinoma (STAD) tissues compared to adjacent normal tissues, but lower in colon adenocarcinoma (COAD), liver hepatocellular carcinoma (LIHC), and pancreas invasive ductal carcinoma (PAAD)." (PMID 40918116, 2025). "Expression of CD68/CD163 in esophageal cancer tissues and adjacent tissue." (PMID 25144454, 2014). "Moreover, based on the Cox model analysis, we found that the higher infiltrating density of CD68+ macrophages in tumor nest was associated with a poor survival, but in tumor stroma was significantly associated with better survival of stage II+III esophageal cancer patients." (PMID 27736796, 2016).
Hernia (7 papers, 2017 to 2025). "Since hernia resorption has been linked to an inflammatory response and particularly to macrophage infiltration, the presence of macrophages and T-lymphocytes that had infiltrated the hernia was also analysed through the immunolocalization of CD68 and CD3, respectively." (PMID 34502517, 2021). "Also, we quantified the number of CD68+ macrophages present in the hernia and consistently found fewer macrophages in the macrophage-administered group, albeit the differences were not statistically significant." (PMID 37429889, 2023). "Also, we found that the number of CD68+ macrophages within the hernia as well as cell apoptosis within the tissue were both proportional to the hernia volume." (PMID 30400975, 2018). "To explore this hypothesis, we analyzed the presence of macrophages and B lymphocytes within the hernia, by measuring immunoreactivity against CD68(ED1) and Pax5, respectively." (PMID 28297581, 2017). "The constant percentage of CD68+ cells in the hernia may occur because only a certain number of cells will be recruited and activated per area of hernia, maintaining the tissue homeostasis." (PMID 28297581, 2017). "Macrophage infiltration (CD68, CD192, CD163), MC classification on MRI, and hernia parameters were analyzed." (PMID 40248336, 2025). "Using the same model, we further confirmed that the number of CD68+ macrophages in the hernia was proportional to its size and hypothesized that only a certain number of macrophages will be recruited and activated per area of hernia, keeping the tissue homeostasis." (PMID 30400975, 2018). "Surprisingly, we found an increase in Pax5+ B lymphocytes in situ in the hernia, but CD68+ macrophages were not altered between groups." (PMID 28297581, 2017). "CD68+ cells were observed in 33% of AIS samples, in 24% of contained hernias and in 11.7% of uncontained samples, but not in protused hernias." (PMID 35039075, 2022).
injury (7 papers, 2012 to 2025). Damage inflicted on the body as the direct or indirect result of an external force, with or without disruption of structural continuity. "In females, radiation-induced cognitive injury was associated with increased CD68 levels, while in males, radiation-induced cognitive injury was associated with reduced CD68 levels." (PMID 30914962, 2019). "In a mouse model of traumatic brain injury, a single dose of telmisartan given 6 h after injury caused reduced perilesional staining for CD68, ionized calcium binding adaptor molecule 1 (Iba-1), and myeloperoxidase (MPO) at 72 h, while a similar treatment 24 h after injury had no such effect." (PMID 27562117, 2016). "Previous studies have reported that hepatic macrophages, which mainly express F4/80 or CD68, are responsible for the aggression of acute liver injury." (PMID 35739966, 2022). "Similarly, the area occupied by CD68+ cells increased in the first 24 h after perinatal brain injury (0.35 ± 0.12% of total area; p = 0.0009)." (PMID 30898154, 2019). "In conclusion, following traumatic brain injury, EPO significantly decreased the number of apoptotic cells, the expression of MCP-1, the infiltration of CD68+ cells as well as brain edema to protect the brain." (PMID 23226759, 2012). "NUDT21 depletion in CD68-expressing cells does not affect LPS-induced Lung Injury." (PMID 41282183, 2025).
lung squamous cell carcinoma (7 papers, 2020 to 2024). "Additionally, squamous cell lung cancer was characterized by a higher content of CD68+ macrophages (p = 0.0343) and FOXP3+ regulatory T cells (p = 0.0014), compared with adenocarcinomas." (PMID 32933105, 2020).
myositis (7 papers, 2012 to 2025). "In the patients with myositis, CD68-positive macrophages and CD4-positive and/or CD8-positive T cells were observed more frequently than CD20-positive B cells." (PMID 41131373, 2025). "Increasing evidence of CD68+ staining in myositis has been reported in studies showing that both CD4+/CD8+ and CD68+ macrophages are present in muscle biopsy specimens from patients with ICI-induced myositis and myasthenia gravis." (PMID 36358686, 2022). "Comparison of HRS-induced myositis in WT versus CD4-Cre.MyD88fl/fl conditional KO mice demonstrates significant reduction in the severity of myositis that reflects diminished infiltration of both CD3+CD4+ T cells and CD3-CD4-CD45+ non-lymphoid cells that include CD68+ macrophages." (PMID 37809058, 2023).
silicosis (7 papers, 2022 to 2025). Silicosis is a respiratory disease caused by breathing in (inhaling) silica dust. "We observed increased numbers of p21+\CD68+ cells after SiO2 administration, thereby supporting the role of macrophages in senescence-associated silicosis." (PMID 35959439, 2022). "Compared with that in control mice, CD68 expression was markedly upregulated in the lung tissue of mice with silicosis." (PMID 38454505, 2024). "To verify the distribution of macrophages, we constructed a 28-day silicosis mouse model and examined CD68 (a macrophage marker) expression in the lung tissue." (PMID 38454505, 2024). "IHC staining showed that CD68 and iNOS, which are pro-inflammatory markers in macrophages, were remarkably expressed in the lung of rats with silicosis." (PMID 37381044, 2023). "It was found that CD68 and APP interacted with CD74 on CD31 in the silicosis group and the Tet group, but not in the normal group, the H2 group and the H2 + Tet group." (PMID 41561355, 2025).
soft tissue sarcoma (7 papers, 2012 to 2023). A malignant neoplasm arising from muscle tissue, adipose tissue, blood vessels, fibrous tissue, or other supportive tissues excluding the bones. "In this study, we subjected surgical specimens of 75 soft-tissue sarcomas to immunohistochemical examination and counted the number of the infiltrating CD68-positive macrophages (total macrophages) and CD163- and CD204-positive macrophages (TAMs)." (PMID 36690825, 2023). "A previous study reported that, in soft tissue sarcoma patients whose biopsy specimens contained large number of CD68-positive macrophages, the resected specimen had few viable tumor cells, suggesting a good response to neoadjuvant chemotherapy." (PMID 33479294, 2021). "The number of CD68-, CD163-, and CD204-positive macrophages in the intratumoral and marginal areas of 75 soft-tissue sarcoma specimens was counted." (PMID 36690825, 2023). "The discrepancy found with soft tissue sarcomas, in which CD163+ macrophages dominate over CD68+ macrophages, could be explained by the fact that CD68 is not only a macrophage-marker, but also, in the context of bone tissue, a marker of osteoclastic cells." (PMID 33498676, 2021).
tuberculosis (7 papers, 2016 to 2025). A chronic, recurrent infection caused by the bacterium Mycobacterium tuberculosis. "Within tuberculosis granulomas, CD68 expression is widespread and multinucleate giant cells also express CD68." (PMID 28570642, 2017). "In tuberculosis, CD68 has been used as a marker for phagocytotic cells before." (PMID 37509363, 2023). "Overexpression of IL-10 by macrophages and monocytes (under control of the CD68 promoter) was shown to induce the expression of Arg1 and other markers associated with alternative macrophage activation during M. tuberculosis infection, increasing host susceptibility to TB." (PMID 27849167, 2016).
asthma (6 papers, 2014 to 2025). "We quantified macrophage subsets in bronchial biopsies of asthma patients using interferon regulatory factor 5 (IRF5)/CD68 for Th1-associated macrophages, CD206/CD68 for Th2-associated macrophages and interleukin 10 (IL10)/CD68 for anti-inflammatory macrophages." (PMID 35387061, 2021). "Tissue specificity was evident: megakaryocytes (PPBP+, Cluster 15) were exclusive to asthma PBMCs (2.1% of cells), while macrophages (CD68+, Cluster 18) dominated AD CSF (8.7% vs." (PMID 40951943, 2025). "There was a significantly greater number of subepithelial CD68+ cells present in subjects with asthma than in normal subjects at day 4 (P = .021)." (PMID 24457412, 2014). "Elastase-positive neutrophils and CD68+ monocytes/macrophages appeared to be more frequent in the bronchial mucosa of subjects with asthma during acute infection compared with baseline." (PMID 24457412, 2014). "We demonstrated that compared with normal subjects, subjects with asthma and RV infection had an exaggerated bronchial mucosal inflammatory response particularly characterized by increased numbers of neutrophils and CD68+ monocytes/macrophages." (PMID 24457412, 2014). "The changes in subepithelial CD68+ cell counts from baseline to day 4 infection in subjects with asthma were also significantly greater than those in normal subjects (P = .025)." (PMID 24457412, 2014). "Compared with baseline, the number of subepithelial CD68+ cells in both normal subjects (P = .018) and subjects with asthma (P = .009) were significantly increased at day 4 of acute infection." (PMID 24457412, 2014). "In conclusion, our study revealed that BT was effective in 81% of patients irrespective of asthma endotypes and was associated with a reduction in ACTA2 and an increase in FAP, COL1A1, COL1A2 and CD68 gene expression." (PMID 35534846, 2022). "In contrast, the present study shows that acute RV infection increases the number of subepithelial CD68+ cells of subjects with and without asthma." (PMID 24457412, 2014).
brain tumors (6 papers, 2013 to 2023). "Our previous study also showed that CD68+ TAMs constitute a major component of the tumor stroma with a predominantly diffuse pattern in GL261 mouse brain tumors." (PMID 37234161, 2023). "CD68+ TAMs correlated with favorable prognosis in several organs, such as prostate, lung, and brain tumors." (PMID 32607685, 2020).
carcinoma in situ (6 papers, 2016 to 2025). "We also observed that CD68, a human macrophage marker, increased in invasive carcinomas compared to in situ carcinomas in the SCAN-B dataset." (PMID 40470186, 2025). "The tumor is composed of mononuclear cells (frequently positive for epithelial markers), osteoclast-like giant cells (positive for CD51, CD68 and CD54) and an identifiable usual urothelial neoplasia (carcinoma in situ, papillary, or invasive carcinoma) in variable percentages." (PMID 31375071, 2019).
Cerebral ischemia (6 papers, 2012 to 2022). Restriction of arterial blood supply to the brain associated with insufficient oxygenation to support the metabolic requirements of the tissue. "Cerebral ischemia caused a reduction in neuron-related NeuN protein, with increases in both macrophage/microglia-related CD68 protein and astrocyte-related GFAP protein levels." (PMID 34073455, 2021). "Brain ischemia and reperfusion induced the presence of a large number of CD68 positive cells in the brain." (PMID 35547761, 2022). "The intensity of CD68 staining was increased with the time after the brain ischemia and was inhibited by 0.5 mg/kg cFLFLF given intravenously at the onset of reperfusion." (PMID 35547761, 2022). "Cerebral ischemia and edema are frequently associated with neuroinflammation, augmented production of proinflammatory mediators, and infiltration of inflammatory cells (e.g., MPO+ neutrophils and CD68+ monocyte/macrophages)." (PMID 24828425, 2014). "Cells that are positively stained for both CD68 and FPR1 in the spleen of a mouse with brain ischemia were increased dramatically after reperfusion." (PMID 35547761, 2022). "In control conditions, microglia do not express CD68, while after brain ischemia, activated microglia have been found positive for CD68." (PMID 33246465, 2020). "The injured cortical tissues of rats with cerebral ischemia exhibited decreased protein expression of neuron-related MAP-2 and SNAP25, though there was evidence of the increased protein expression of macrophage/microglia-related CD68 and astrocyte-related GFAP." (PMID 34943061, 2021). "This inhibition may not be due to the decrease of passive permeability of CD68 positive cells through impaired blood-brain barrier because mice treated with cFLFLF had a degree of blood-brain barrier permeability increase similar to that of mice without cFLFLF after brain ischemia." (PMID 35547761, 2022).
chronic kidney disease (6 papers, 2013 to 2025). Impairment of the renal function secondary to chronic kidney damage persisting for three or more months. "CD68-positive cells indicated the infiltration of macrophages, a sign of inflammation, and a common feature of most human chronic kidney diseases." (PMID 35084555, 2022). "We evaluated the predictive value of immunohistochemical staining for α-smooth muscle actin (SMA), Wilm’s tumor 1 (WT1), CD68, and cytokeratin for end-stage renal disease (ESRD)." (PMID 23773275, 2013). "Furthermore, chronic kidney disease is accompanied by increased CD68-positive cells between adipocytes, which is intriguing due to the positivity for CD-68 of foamy cells in the kidney." (PMID 41301812, 2025). "To investigate the role of P2Y12 in chronic kidney disease (CKD)-related AVF failure, we initially assessed the expression of P2Y12 and related genes such as TGF-β1, MCP-1, and CD68 in the stenotic venous tissues of the experimental group and the cephalic veins of the control group." (PMID 38532720, 2023).
classical Hodgkin lymphoma (6 papers, 2013 to 2024). "CD68+ tumor-associated macrophages (TAM) play an important role in the progression of classical Hodgkin lymphoma (cHL)." (PMID 32019558, 2020). "Given the potential role for TAMs in immune suppression in classic Hodgkin’s lymphoma (cHL), PD-L1 upregulation in CD68+ TAMs was recently shown to occur only when these cells were in close proximity to CD30+ PD-L1+ Reed-Sternberg cells." (PMID 26885371, 2016). "CD68 is a marker of pan-macrophages, and previous reports demonstrated that increases of intrafollicular CD68-positive macrophages are related to poor prognosis in FL and classical Hodgkin's lymphoma (CHL)." (PMID 24236041, 2013). "Regarding the expression levels of CD68 as a M1-TAM marker in carcinomas and prognosis, it has been reported that the low expression of CD68 and CD163 in classical Hodgkin lymphoma indicates a better prognosis." (PMID 39199574, 2024).
cognitive decline (6 papers, 2019 to 2025). "This is supported by a study showing that HF diet-induced cognitive decline was associated with an increase in microglia activation and phagocytic activity (CD68+) in the hippocampus." (PMID 37208759, 2023). "Moreover, it has been suggested that CD68 could play a role associated with cognitive decline in a subgroup of the normally aged population." (PMID 36979402, 2023). "When performing sensitivity analyses for cell type fraction leveraging the abundance of cell-specific single gene markers (e.g., ENO2 for neurons, GFAP for astrocytes, CD68 for microglia), PLD3 associations with β-amyloid and cognitive decline remained significant (p<0.05)." (PMID 33830999, 2021). "Of note, a previous study by our group in the immunised group showed that neuronal loss is correlated with Iba1-positive microglia and phagocytic CD68-positive microglia associated with pro-apoptotic neurons, but without accelerated cognitive decline compared to non-immunised AD patients." (PMID 31703599, 2019). "EE has also been shown to decrease IL-1β and CD68 expression in the hippocampus, as well as prevent cognitive decline in aged mice, even in the absence of running wheels." (PMID 35112705, 2022).
colorectal tumor (6 papers, 2019 to 2025). "IHC of CD45 and CD68 were employed to assess leucocytes and macrophages infiltration into colorectal tumor." (PMID 31528237, 2019). "Recent work by Yank and colleagues describes an association between higher CD163+/CD68+ ratio at the IF of colorectal tumors and poor prognosis, which is not in accordance with our data." (PMID 31481956, 2019). "In Visium spatial transcriptomics of human colorectal tumours, there were hotspots enriched in monocyte/macrophage genes (including CD14+CD68+), and expression of CXCL9 and CXCL10 were localised to these regions." (PMID 40523200, 2025).
dyslipidemia (6 papers, 2012 to 2025). "Our finding that EAT from obese patients was more abundant in PAR4 and both CD68 and CD54 suggests that the causal interaction between PAR4 and WAT inflammation seen in mice also occurs in the clinical context of metabolic syndrome." (PMID 38652276, 2024). "Specifically, we emphasize the influential role of inflammation, as indicated by CD68 analysis, which is influenced by factors such as smoking habits, severe dyslipidemia, and subsequent macrophage infiltration." (PMID 37744724, 2023). "Despite higher plasma cholesterol, triglycerides and early signs of a metabolic syndrome in the HFD mice, CD68-staining, Oil Red O and collagen contents were not significantly different between the two regression groups." (PMID 26046657, 2015).